LOX (lysyl oxidase)
Diseases named in the same sentence as LOX in open-access papers (continued):
Sharing a sentence is not in itself a finding about the gene and the disease.
tumor (continued). "Among the regulators involved in tumor metastasis, lysyl oxidase (LOX) is an important contributor for tumor invasion, migration and the formation of the pre-metastatic niche." (PMID 29472856, 2018). "Paradoxically, LOX has been reported to function both as a tumor suppressor and a promoter in human cancer cells, depending on tumor type and stage of progression." (PMID 30701028, 2018). "Stromal or tumor cell-derived LOX expression has also been reported to play an important role in angiogenesis and tumor metastasis." (PMID 30701028, 2018). "As collagen is the substrate of LOX, we monitored collagen deposition using picrosirius red staining of tumor sections, and quantified the signals under polarized light." (PMID 28574510, 2017). "Primary tumours produce factors such as lysyl oxidase, PlGF, and exosomes that prepare the secondary site for the arrival of disseminated tumour cells in what is termed the premetastatic niche." (PMID 28210073, 2017). "Despite the growing evidences of LOX contribution to the establishment of a protumorigenic microenvironment, there is very few information available about tumor stroma-derived LOX." (PMID 28553358, 2017). "In terms of molecular mechanisms leading to ENS, recent studies have evaluated a possible role for lysyl oxidase in tumor hypoxia." (PMID 28837620, 2017). "Formation of tube-like structures in vitro by pericytes was also significantly impaired upon inhibition of LOX/LOXL activity with βAPN, which induced more prominent effects in tumor-associated pericytes." (PMID 28553358, 2017). "For many types of cancer, increased LOX activity promotes metastasis of cancer cells and progression of tumor growth." (PMID 28110559, 2017). "Adaptation to hypoxia is a driving force for tumor progression whereby hypoxia stimulates the hypoxia-inducible factor 1α (HIF-1α)-mediated LOX expression." (PMID 28425924, 2017). "The expression and localisation of LOX was investigated in normal mucosa, primary tumour tissue and lymph node metastases by immunohistochemistry (IHC)." (PMID 28947950, 2017). "The lysyl oxidase gene (LOX), one of the overexpressed genes among a tumor hypoxia signature, was shown to be directly regulated by HIF-1α transcription factor and is essential for hypoxia-induced metastasis and cancer cell proliferation." (PMID 28143503, 2017). "Nevertheless, our data suggest that like BAPN, CCT365623 is a LOX inhibitor that modulates the biological functions of LOX in cells and has anti-tumour activity in mice." (PMID 28416796, 2017). "The mice that received shRNA control cells had substantial tumour burden in the lungs, whereas lung tumour burden was substantially lower in mice that received LOX-depleted cells." (PMID 28416796, 2017). "The significant inhibition of migration and angiogenic properties of pericytes detected upon inhibition of LOX/LOXL activity with the inhibitor βAPN is in agreement with a previous study reporting inhibition of tumor angiogenesis by βAPN treatment in vivo." (PMID 28553358, 2017). "Nuclear LOX expression was significantly increased in patient lymph node metastases compared to their primary tumours." (PMID 28947950, 2017). "LOX has been shown to promote cancer cell proliferation, metastasis and angiogenesis, supporting a role for LOX as a tumour and metastasis promoter." (PMID 28947950, 2017). "In line with the results obtained in patient tumour tissue above, LOX was detected both in the cytoplasm and in the nucleus of all three cell lines." (PMID 28947950, 2017). "High nuclear LOX expression in tumours was correlated with a high rate of distant metastasis and increased recurrence." (PMID 28947950, 2017). "The tumor matrix typically consists of excessive levels of fibrous collagen, which can be additionally crosslinked by soluble mediators such as lysyl oxidase (LOX), thereby elevating matrix stiffness." (PMID 28694244, 2017).
tumor (continued). "Immunohistochemical staining for the endothelial marker endomucin revealed a significant decrease in tumor angiogenesis and vessel count in both the dual LOX/LOXL2 inhibitor treated mice (PXS-S1A) and the LOXL2 specific inhibitor treated mice (PXS-S2B)." (PMID 28199967, 2017). "We have shown that nuclear LOX expression was significantly increased in lymph node metastases compared to primary tumours, and that this high nuclear expression was correlated with distance metastasis." (PMID 28947950, 2017). "Critically, we observe significantly less staining of MATN2 and EGFR in the plasma membranes of the cells in the LOX-depleted tumours than in the cells of shRNA control tumours." (PMID 28416796, 2017). "Upon inhibition of LOX/LOXL activity, a significant reduction in migration of both normal and tumor-associated pericytes was detected." (PMID 28553358, 2017). "Although these two processes involve interaction with the tumor stroma, thus far, very little is known about LOX expression in cellular components of the TME, and data on LOX expression in pericytes is lacking." (PMID 28553358, 2017). "Here, we find that LOX regulates the epidermal growth factor receptor (EGFR) to drive tumour progression." (PMID 28416796, 2017). "In contrast, knocking down of LOX expression in the SW620 metastatic cell line significantly reduces tumour cell proliferation and metastasis." (PMID 28947950, 2017). "Increasing evidence indicates that the tumour suppressor activity of LOX lies in the cleaved LOX-PP (18-kDa) which can re-enter the nucleus following extracellular cleavage from the mature enzyme and repress oncogenes such as bcl-2." (PMID 28947950, 2017). "Under hypoxic conditions, the increased expression of LOX enzyme correlates with tumor invasiveness." (PMID 28143503, 2017). "This SNP located in a highly conserved region within LOX-PP has been associated with attenuated ability of LOX-PP to oppose the effects of LOX, resulting in tumor cell invasive phenotype." (PMID 28143503, 2017). "In the present study, our data showed the increased expression of LOX in the nucleus of the matched patient lymph node metastases compared to primary tumour." (PMID 28947950, 2017). "Although LOX is over-expressed in several cancers and was shown to enhance tumor progression, its reduced expression in some cancers indicates a tumor-suppressor function." (PMID 29254206, 2017). "Nuclear LOX expression in the primary tumour was also positively correlated with phospho-NF-κB p65 (Serine 536) expression (P < 0.001), and showed a weak, albeit statistically significant positive correlation with Ki-67 expression (P = 0.05)." (PMID 28947950, 2017). "Targeting tumor stiffness via the inhibition of LOX activity has been shown to decrease tumor growth, malignancy, and metastasis in mice." (PMID 28694244, 2017). "We therefore suggest that the tumour promoting role of LOX in the tumour microenvironment decreases with time in tumour-types with a high capacity to stimulate degradation of the ECM." (PMID 26804196, 2016). "Further, the role of LOX in tumor microenvironment remodeling, tumorigenesis, and metastasis and the underlying mechanisms have also been elucidated." (PMID 28036074, 2016). "The effect of dietary components on LOX activity and the possibility of using LOX as a tumor therapy target have also been discussed." (PMID 28036074, 2016). "Lysine is a very dynamic amino acid in the proteins, being oxidized by lysyl oxidase (LOX) an enzyme whose functional significance on tumor progression and metastasis is known." (PMID 27823983, 2016). "Recently, a number of studies have shown that LOX is overexpressed in most cancers and that it is involved in the regulation of tumor progression and metastasis." (PMID 28036074, 2016). "Our results suggest that the enzymatic activities of LOX proteins are important for tumour progression during the early stages of tumour establishment, as BAPN treatment at this point inhibited tumour growth." (PMID 26804196, 2016).
tumor (continued). "Fibrillar collagen is the principal structural component of the ECM surrounding solid tumors, and it has been demonstrated that collagen cross-linking by lysyl-oxidase (LOX) enzymes promotes tumor cell invasion, stromal activation and desmoplasia." (PMID 26716418, 2016). "Inhibition of LOX expression has been shown to improve drug diffusion and increase the efficacy of cytotoxic treatment in 3D tumor models." (PMID 28036074, 2016). "In AT-1 tumours, LOX expression varied within the tumours—with both nuclear and cytoplasmic staining." (PMID 26804196, 2016). "In animal models, LOX expression leads to osteolytic lesion formation prior to the arrival of tumor cells." (PMID 27706047, 2016). "We therefore require a better understanding of these phenomena in order to identify tumours that are suitable for anti-LOX treatment and in what context, and also the circumstances under which LOX functions as a tumour suppressor." (PMID 26804196, 2016). "The effects of BAPN treatment in vivo are therefore probably due to inhibition of LOX activities in the tumour stroma and in the surrounding prostate tissue." (PMID 26804196, 2016). "A temporal decrease in collagen fibre content, which is a target for LOX, was observed in tumours and in the tumour-adjacent prostate tissue." (PMID 26804196, 2016). "Despite the fact that enough evidence indicates that LOX enhances tumor progression, several studies have also showed that LOX acts as a tumor suppressor gene." (PMID 28036074, 2016). "This loss of collagen in the surrounding non-malignant tissue was also observed at day 7, suggesting that collagens were reduced in the tumour-adjacent tissue when LOX inhibition was initiated for the established tumours." (PMID 26804196, 2016). "While the enzymatic activity and transcriptional activating properties belong to the 32-kDa LOX protein, the tumor suppressing ability of the LOX gene is from the 18-kDa LOX-PP." (PMID 28036074, 2016). "Our data suggest, that cellular distribution of LOX protein expression in ccRCC tissue also affects the aggressiveness of the tumor." (PMID 27336447, 2016). "B6H12-treated bCSCs showed an up-regulation of thioredoxin-interacting protein (TXNIP) and LOX (lysyl oxidase), which are known tumor suppressors." (PMID 26840086, 2016). "This illustrates the complex and somewhat paradoxical roles of LOX enzymes during tumour progression." (PMID 26804196, 2016). "Lysyl oxidase (LOX) is an extracellular matrix-remodeling enzyme that plays important roles in tumor development and progression." (PMID 26882568, 2016). "LOX-mediated cross-linking of the ECM has also been shown to promote tumor progression by enhancing integrin signaling, which can inhibit cancer cell apoptosis, regulate cancer stem cell function and growth factor signaling." (PMID 26956475, 2016). "LOX-mediated collagen crosslinking can also promote tumor progression and invasion by increasing extracellular matrix stiffness." (PMID 26908052, 2016). "Similar to the LOX proteins, urokinase (uPA) has also been shown to have key functions in tumor progression." (PMID 26956475, 2016). "It should be noted, however, that according to more recent studies, LOX functions to promote tumor growth and metastasis, and is a target for the development of anti-cancer drugs." (PMID 26968815, 2016). "The results in this study suggest that LOX levels should perhaps be related to collagen content in tumours and the tumour-bearing organ in order to elucidate its role in individual patients." (PMID 26804196, 2016). "This type of tumour grows in a poorly developed stroma, and LOX expression in the tumour stroma was therefore difficult to evaluate." (PMID 26804196, 2016). "LOX plays a fundamental role in metastasis, including the formation of the pre-metastatic lesions in bone that are colonized by circulating tumor cells and expand into occult osteolytic metastases." (PMID 26567111, 2016).
tumor (continued). "The by-product produced upon cleavage of the LOX proenzyme has also been shown to have tumor suppressive properties." (PMID 26501565, 2015). "Further studies are needed to clarify differential LOX function in normal and tumor tissues as well as in distinct intracellular compartments." (PMID 25790191, 2015). "Of note, LOX expression has paradoxical roles in tumor suppression and tumor progression, depending on cellular location, type, and transformation status." (PMID 25885919, 2015). "To understand the mechanism of action of the LOX-blocking antibody and the increased benefit with gemcitabine, we next analyzed the tumor and stroma from these mice." (PMID 26077591, 2015). "Altogether, these studies indicate that LOX plays an important role in Ewing pathogenesis by acting as a tumor suppressor gene." (PMID 26258070, 2015). "In fact, it has been reported that LOX activity is involved in many biological functions other than collagen cross-linking, such as metastasis, tumor cell growth, cell migration and motility, angiogenesis, cell signaling, and transcription." (PMID 26347346, 2015). "In hypoxic conditions, hypoxia inducible factor-1α (HIF-1α) induced LOX expression and facilitated tumor migration, invasion, and metastasis in a range of cancers." (PMID 26579497, 2015). "Initially proposed to act mainly as a tumor suppressor, members of the LOX enzyme family are gaining relevance in their role as promoters of tumor progression and metastasis." (PMID 26265048, 2015). "The high expression level of LOX in all cell lines and tumor tissue homogenates is an important finding for subsequent molecular targeting experiments of LOX using [18F]FB-GGGDPKGGGGG-NH2 and FITC-Ava-GGGDPKGGGGG-NH2." (PMID 26265048, 2015). "LOX inhibition also synergized with gemcitabine to kill tumors and significantly prolonged tumor-free survival in KPC mice with early-stage tumors." (PMID 26077591, 2015). "We here show that hypoxia significantly up-regulated LOX mRNA expression in human prostate epithelial cells and prostate myofibroblasts in vitro, and human prostate tissue (both tumor and surrounding normal) is generally hypoxic." (PMID 26501565, 2015). "LOX has been identified as an important regulator of the hypoxia-induced tumor progression pathway through a HIF-1α-dependent mechanism in numerous cancer types, such as breast, head and neck, prostate and renal cell carcinomas." (PMID 25790191, 2015). "Novel relationships between LOX expression in tumor epithelium and pEGFR, pAKT and hyaluronan were also found." (PMID 26501565, 2015). "This suggests novel relationships between LOX expression in the tumor and prostate TINT epithelium and these factors." (PMID 26501565, 2015). "The first experimental condition was type 1 collagen crosslinking, a condition chosen because covalent collagen crosslinking of the stroma mediated by lysyl-oxidase (LOX) has been found to promote tumour progression in mice." (PMID 26472542, 2015). "Aberrant LOX, LOXL2, and LOXL4 expression are implicated in dysregulating the ECM and inducing a malignant phenotype and promoting tumor progression in EOC." (PMID 26579497, 2015). "This fits well with our data where tumor cell secretes LOX and suggests it is the cross-linking of collagen that is critical in defining the pro-tumorigenic quality of the stromal." (PMID 26077591, 2015). "Further studies are needed to examine this possibility and the relative importance of tumor vs. TINT secreted LOX." (PMID 26501565, 2015). "Tumor spheroids from control transfected and LOX/LOXL2 overexpressing 4T1 cells were generated and cultivated at 20% oxygen levels to keep interferences by endogenous lysyl oxidases at a minimum." (PMID 26620400, 2015). "Increased extracellular LOX activity therefore results in a stiffer microenvironment that promotes tumor progression, metastasis, and invasion." (PMID 26501565, 2015).
tumor (continued). "LOX-secretion along with enzymatic activity was investigated in multiple tumor cell lines in response to irradiation." (PMID 25052686, 2014). "The choice of serum tumor markers to be combined with LOX requires further investigation to determine how to improve the sensitivity of these biomarkers in the detection of metastasis in GC." (PMID 25060181, 2014). "Collagen I, a component of both desmoplastic tumor stroma and organ fibrosis is a major substrate for LOX and has been shown to be a key component of both primary and metastatic tumor microenvironments." (PMID 24885752, 2014). "On the other hand, increased expression of LOX and LOXL2 is associated with aggressive tumours, decreased survival, and increased metastasis in cancer of the colon, breast, lung, prostate, and others." (PMID 25141126, 2014). "Protease dependent-ECM remodeling is predominantly catalyzed by enzymes such as lysyl oxidase (LOX), synthesized by either stromal cells during early stages of carcinogenesis, or tumor cells during late stages of tumor progression in response to hypoxia." (PMID 24338768, 2014). "We carefully selected other serum tumor markers correlated with tumor invasion and combined these with LOX to improve the sensitivity of these in detecting metastasis in GC." (PMID 25060181, 2014). "Relative LOX mRNA expression was quantified in primary tumour tissue samples of 105 patients and in one lymph node metastasis each for 17 of these patients." (PMID 25141126, 2014). "The LOX expression level and the serum concentration of the four tumor markers were evaluated preoperatively." (PMID 25060181, 2014). "Locally applied irradiation to tumor xenografts also increased LOX-secretion in vivo and resulted in enhanced LOX-levels in the murine blood serum." (PMID 25052686, 2014). "LOX is essential in driving tumor cells escape from primary site, extravasation and growth at secondary sites during metastasis." (PMID 24338768, 2014). "LOX is a copper-dependent amine oxidase whose expression in the extracellular matrix is closely correlated with tumor development, progression, adhesion, malignant transformation and invasion." (PMID 25174950, 2014). "We detected increased LOX-staining in tumor sections irradiated with both regimens of IR, with more enhanced LOX-staining at the 48 hour time point after irradiation." (PMID 25052686, 2014). "In this study, we demonstrated that LOX tumor cell secretion is promoted by IR in vitro and in vivo and that IR-induced LOX functionally promotes invasion of cancer cells in vitro." (PMID 25052686, 2014). "Mean LOX mRNA levels in primary tumours were 2.7±2.5-fold higher than in corresponding, paired lymph node metastases, and the median levels were 2.3-fold higher (p = 0.002, paired t-test)." (PMID 25141126, 2014). "In contrast, extracellular LOX is mostly pro-tumorigenic and pro-metastatic, particularly via remodelling the extracellular matrix of the tumour microenvironment." (PMID 25141126, 2014). "To confirm these findings in vivo, we analyzed LOX secretion in A549-derived tumor xenografts in mice." (PMID 25052686, 2014). "Reduced LOX expression has been observed in many carcinomas, and the ectopic expression of LOX inhibited tumour progression in several experimental model systems." (PMID 25141126, 2014). "Previous studies have suggested that tumor stroma stiffness can be mediated by LOX-mediated crosslinking." (PMID 25076207, 2014). "Lysyl oxidase (LOX) is an important tumor-secreted factor participating in creating a suitable niche to support disseminated tumor cell growth via promoting formation of a mature ECM and regulating fibronectin activity through FAK activation." (PMID 24587996, 2014). "LOX is considered as a tumor suppressor gene as evidenced by that expression of transfected LOX cDNA suppressed Ha-ras-induced cell transformation indicating a ras-suppressor effect of LOX." (PMID 25546273, 2014).